CTLA4 (cytotoxic T-lymphocyte associated protein 4)
Diseases named in the same sentence as CTLA4 in open-access papers (continued):
Sharing a sentence is not in itself a finding about the gene and the disease.
tumor (continued). "Drugs targeting CTLA-4, such as ipilimumab and tremelimumab, have been developed and have displayed promising anti-tumor effects." (PMID 35614201, 2022). "In mice experiments with ADT and various combinations of PD-1 and CTLA-4 inhibitors, tumor volume at day 30 was always larger than the initial tumor." (PMID 35015785, 2022). "Multiple preclinical studies have proposed that Fc effector functions of anti-CTLA-4 therapy are required for anti-tumor efficacy, in part, through the depletion of intratumoral regulatory T cells (Tregs)." (PMID 35237846, 2022). "Immune checkpoint inhibitors (ICIs) enhance the cytotoxicity effect of T cells on tumor cells by acting on co-inhibitory receptors such as CTLA-4 and PD-1 or their ligands such as programmed death ligand-1 (PD-L1)." (PMID 36199434, 2022). "Anti-CTLA-4 antibodies were shown to unlock the immune response to cancer, as well as lead to the depletion of tumor-infiltrating Tregs via antibody-dependent cell-mediated cytotoxicity." (PMID 35634292, 2022). "Since we uncovered that depleted RBMS1 reduces PD-L1 level, thereby promoting anti-tumor T-cell immunity, we chose CTLA4 blockade for the combination therapy with RBMS1 depletion in the mouse 4T1 engraftment model." (PMID 35538152, 2022). "PD1, PD-L1, and CTLA-4 were found to be immune checkpoints responsible for tumor immune escape and key targets of immunotherapy." (PMID 35911380, 2022). "Other tumor types have benefitted from dual-immunotherapy combinations, such as anti-PD-1 and anti-CTLA-4." (PMID 35558159, 2022). "The combined treatment of both G-MDSCs depletion and CTLA-4 inhibitor can achieve an excellent anti-tumor treatment." (PMID 36131911, 2022). "ICIs, involving inhibitors of PD-1, PD-L1, and CTLA-4, can reverse the state of immunosuppression and mobilize the immune cells to attack the tumor instead of targeting the tumor itself." (PMID 36405691, 2022). "An analysis of tumor progression kinetics demonstrated that anti-CTLA4 mAb treatment reduced the tumor volume in NS and LS diet cohorts, as compared to respective isotype controls." (PMID 35741331, 2022). "Previously, the mechanism of tumor-specific Treg depletion was proposed by the presence of FcγR expressing cells and higher surface expression of CTLA-4 on Tregs in the tumor." (PMID 35237846, 2022). "Anti-CTLA-4 and rapamycin treatment during T-cell priming resulted in a considerable decrease in tumor growth and a significant increase in tumor-free survival in mice compared to either therapy alone." (PMID 36428613, 2022). "Tregs inhibit tumor killing by CTLs through TGF-β-dependent cell contact, inhibit the production of memory CTLs via cytotoxic-T-lymphocyte-associated protein-4 (CTLA-4), and induction of CTLs death via granzyme B and perforin-dependent manner." (PMID 36532071, 2022). "On the contrary, cytotoxic T-lymphocyte-associated protein 4 (CTLA4) is a negative regulatory inducible receptor for CD80/CD86 and has inhibitory effects on T cell responses, leading to T cell attenuation and tumor cell immune evasion." (PMID 35656508, 2022). "CTLA-4 blockade on conventional T-cells and regulatory T-cells (Tregs) results in maximal anti-tumor activity compared to unicompartmental blockade of either T-cell population." (PMID 35326731, 2022). "It is more widely expressed than CTLA-4 and can be detected in multiple immune cell types within the tumor microenvironment (TME)." (PMID 36648843, 2022). "When combined with checkpoint inhibition, OMCPmutIL-2 substantially improved survival of mice that received concomitant anti–CTLA-4, resulting in tumor regression in 3 out of 5 mice, while PD-1 blockade potentiated IL-15–based immunotherapy." (PMID 35603788, 2022). "It has been found that monotherapy with antibodies to CTLA-4 can effectively instigate tumor regression of transplantable murine tumors." (PMID 35392976, 2022).
tumor (continued). "A combination of anti-PD-1 and CTLA-4 at the same dose had a greater anti-tumor effect against MC38 tumor in the same study." (PMID 35514996, 2022). "Several studies have also revealed the association of LAYN, CTLA4, and GZMK expression with tumor-infiltrating exhausted CD8+ T cells and a poor prognosis." (PMID 35854246, 2022). "This issue was suggested to be solved by using REQORSA as Fus1/Tusc2-based genetic therapy in mouse model of lung cancer reduced expression of array of IC molecules (TIM-3, CTLA-4, PD-1) concomitant with anti-tumor response." (PMID 35181743, 2022). "The data on anti-RANKL/anti-PD1/anti-CTLA4 combination therapy showed promising results in a higher proportion of tumor-infiltrating CD4+ and CD8+ T cells that can produce both IFNγ and TNFα after anti-RANKL treatment." (PMID 35386705, 2022). "The gut microbiota-dependent DC maturation drives potent tumor-specific immune responses and augments the activity of CTLA-4 and/or PD-L1 blockades." (PMID 35677057, 2022). "Feeding and recolonizing these strains significantly boosted anti-PD1 and anti-CTLA-4 therapeutic responses in tumor-bearing mice, indicating their synergistic role in assisting ICI therapy." (PMID 35252014, 2022). "Tumour‐infiltrating γδ T cells showed exhausted immunophenotypes with high checkpoints expression (CTLA‐4, PD‐1 and PD‐L1)." (PMID 35731974, 2022). "A previous study reported that the partial tumor suppressive effect of anti-PD-1 or -CTLA-4 antibody monotherapy in MC38 tumor-bearing mice which received 4 doses of 200 μg/injection over 10 days." (PMID 35514996, 2022). "CPIs have transformed cancer treatment, with unprecedented and durable anti-tumor response observed with antibodies against key immunological checkpoints such as PD-L1, PD-1, and CTLA-4." (PMID 35697801, 2022). "There are significant differences in tumor immune microenvironment and PD‐1/PD‐L1/CTLA‐4 expression between groups." (PMID 35246970, 2022). "Conversely, dual blockade of the LAG-3 and CTLA-4 pathways using PD-1 knockout mice led to tumor-free survival in 40% of treated mice." (PMID 36077354, 2022). "Anti-CTLA-4 therapy exerts an anti-tumor effect by enhancing the T cell response and producing cytokines such as IFN-γ, an essential cytokine for the host immune response." (PMID 35740355, 2022). "Further, the expression level of immune checkpoint molecules (PDL1, CTLA4, LAG3, TIGIT, CD27, IDO1, ICOS) and tumor mutational burden (TMB) also showed significant differences between the two subtypes, indicating the clinical value of the two subtypes." (PMID 36568197, 2022). "Presuming that this model outcome is a good representation of the evolved tumor situation, this suggests that the inhibition of the CTLA-4 pathway would reactivate a larger population of immune cells than the PD-1 pathway blockade." (PMID 36428963, 2022). "There is also the expression and interaction of immune checkpoint molecules between tumor cells and immune cells to protect cancer cells from the attack of immune cells, such as PD-1, PD-L1, CTLA-4, LAG-3, ID-1 and tim-3." (PMID 35892755, 2022). "Immunotherapy is another tumor therapy strategy based on antitumor immunity activation trough agents as CTLA4 inhibitors (ipilimumab) or PD-1/PD-L1 inhibitors as nivolumab." (PMID 33811514, 2022). "As ICB therapies targeting PD-1/PD-L1 and CTLA-4 have shown promising results in clinical trials, tumor immunotherapy is attracting more attention." (PMID 36253800, 2022). "Several clinical trials are testing the efficacy of anti-CTLA-4 combined with other anti-ICs in a variety of tumor types." (PMID 35164813, 2022). "Overall, treatment with TTFields, anti-PD-1/anti-CTLA-4, or anti-PD-L1 alone provided limited effects on tumor growth, in accordance with the reported poor immunogenicity of this model." (PMID 36430552, 2022).
tumor (continued). "Drugs that block immune checkpoint receptors such as CTLA-4, PD-1 or PD-L1 have revolutionised cancer treatment, with durable anti-tumor responses observed in a subset of cancer patients." (PMID 35634282, 2022). "Administration of cyclophosphamide one day prior to anti-CTLA-4 improved immunological anti-tumor responses." (PMID 36003765, 2022). "A recent review stated that the main immune checkpoints on tumor-infiltrating and peripheral Tregs are CTLA-4, PD-1/PD-L1, LAG-3, TIM-3 and TIGIT." (PMID 36009853, 2022). "At the same time, tumor cells can also promote the expression of immunosuppressive molecules, such as PD-1, PD-L1, PD-L2, CTLA-4, and further inhibit the activation of immune cells." (PMID 35223466, 2022). "Response to anti-CTLA4 was rapid, with visible tumor growth arrest observed between the second and third treatment cycles in most animals, compared to the fourth and fifth cycles for anti-PD1." (PMID 36230753, 2022). "Tumor immune escape within the pancreas and peritoneum, in the absence of immunoediting, triggered tumor expansion, and PD-1 or CTLA-4 checkpoint inhibition was unable to restore antitumor immunity." (PMID 36291050, 2022). "Pan Zheng and Yang Liu in 2018 have shown that the main molecular mechanism of CTLA-4 antibody drugs is to clear the local tumour Treg through the ADCC effect mediated by the Fc CTLA-4 segment, rather than by blocking CTLA-4/B7 interaction." (PMID 36195696, 2022). "Cytotoxic T-lymphocyte antigen-4 (CTLA4) is an immune checkpoint protein expressed on regulatory T (Treg) cells and activated T cells that downregulate T cell activation and suppress anti-tumor immune responses in response to T cell receptor engagement." (PMID 35884975, 2022). "CTLA-4 is a fundamental immunoregulatory molecule that raises the activation threshold of T cells and attenuates the anti-tumor response, which is expressed on the surface of T cells and T regulatory cells (Tregs)." (PMID 36358874, 2022). "Here, preventing the normal function of CTLA-4 heightens activity within the T cell compartment, resulting in durable anti-tumour immune responses in a proportion of patients." (PMID 36119113, 2022). "The synthetic TERT DNA vaccine works synergistically with anti-CTLA-4 therapy to inhibit tumor growth and prolong survival in mouse models that have a weak response to a single immune checkpoint inhibitor (ICI)." (PMID 35903534, 2022). "In the anti-PD-1/anti-CTLA-4 experiment, although myeloid cell infiltration was reduced, PD-L1 expression by these cells, and overall in the tumor, was elevated." (PMID 36430552, 2022). "We evaluated the anti-tumor response when combined with RT and anti-CTLA-4, as compared to the combination of RT and anti-CTLA-4 with fully formed PIC." (PMID 35999216, 2022). "The content of CTLA-4 +PD-1+ tumor-infiltrating cells is correlated with the therapeutic effect of PD-1, and the higher the content is, the stronger the effect." (PMID 36124030, 2022). "Advances in immune checkpoint inhibitors, such as PD-1 and CTLA-4, have brought much attention to the immune cell–tumor crosstalk; however, less is known about the contribution of stromal components to the immune milieu." (PMID 36010899, 2022). "Mice that had been confirmed to have been tumor free for 107 days after initial tumor challenge were compared against age-matched naive mice that received an anti–CTLA-4 boost 3 days after B16.BL6 injection." (PMID 35552271, 2022). "Combination of E-301 with PD-1– and CTLA-4–blocking antibodies augmented the inhibition of tumor growth and delayed time to progression compared with both E-301 and ICB in combination with E-301 LOF." (PMID 36322632, 2022). "Supporting this, we observed improved tumor clearance from 50% to 80% when STING therapy was combined with immune checkpoint inhibition (anti-CTLA4 and anti-PD1)." (PMID 36700206, 2022).
tumor (continued). "In fact, immune checkpoint inhibitors targeting programmed death 1 (PD-1)/programmed death ligand 1 (PD-L1) and CTLA-4 (both of which suppress T-cell proliferation) have shown unprecedented, sustained responses in certain tumor types." (PMID 35892678, 2022). "The anti-CTLA-4 antibody has been used to block the CTLA-4 to induce T cell activation, which inhibits tumor growth." (PMID 35273607, 2022). "Current evidence suggests that the application of immune checkpoint inhibitors such as PD-1/PD-L1 and CTLA-4 and the combination of immunization and standard chemotherapy significantly prolong the survival of tumor patients." (PMID 35965524, 2022). "The combination of FeNP-based MHT with local injection of nano-adjuvants and systemic injection of anti-CTLA4 can lead to systemic therapeutic responses to inhibit tumor metastasis." (PMID 36032103, 2022). "Research suggests that blocking the CTLA-4 inhibitory signal that leads to the reduction in Treg cells at tumor locations is critical for CTLA-4 mAb-mediated anticancer activity." (PMID 35954362, 2022). "On the other hand, anti-CD96 combined with adriamycin chemotherapy, anti-CTLA-4, or anti-PD-1 exhibited more effective inhibition of tumor metastasis in three different tumor models." (PMID 35606854, 2022). "In this long process, tumor cells express more PD-L1 and CTLA-4 and reduce the expression of major histocompatibility complex (MHC) class I tumor-associated antigens to become less immunogenic and hence avoid immune identification." (PMID 35681656, 2022). "These included genes consistent with pro-inflammatory immune responses (CD27, CD28, CD3e, CD8a, ICOS, ICOSLG, Pax5, TBX, GATA3, HLA-A, TNFSF14, GPR146), but also immune suppressive influences in the tumor immune microenvironment (CTLA-4, FoxP3, PD-1)." (PMID 36698398, 2022). "An additional approach to moderate the adverse event profile of anti-CTLA-4 is to limit the CTLA-4 blockade within the tumor." (PMID 36198685, 2022). "Increased CTLA-4 expression in circulating CD4+ T cells from colorectal cancer patients was found to be positively correlated with tumor-node-metastasis (TNM) staging." (PMID 36612180, 2022). "The broadest impact comes from immune checkpoint blockade (ICB) that reinvigorates anti-tumor cytotoxic T lymphocytes (CTLs) using antibodies against CTLA4 or PD1/PD-L1 and generates therapeutic responses across a variety of cancer types." (PMID 36341371, 2022). "CTLA-4 inhibitors can block the binding of CTLA-4 with its ligand on the surface of APCs, thereby blocking the inhibitory immune signal and restoring the anti-tumor immune effect of the body." (PMID 36466873, 2022). "The frequency of circulating CD3+CTLA-4+ cells positively correlated with a poor pathologic response to neoadjuvant treatment determined by tumour regression grade using the Mandard scoring system (p = 0.04)." (PMID 35366537, 2022). "At the same time, resveratrol and curcumin can also reduce the expression levels of CD28 and CD80 in CD4+ T cells, up-regulate the expression of CTLA-4, and regulate tumor growth." (PMID 36505462, 2022). "Unlike PD-1, which acts at later stages of T cell activation and typically in the tumor microenvironment, CTLA-4, another immune checkpoint, acts earlier in the immunity cycle." (PMID 36466910, 2022). "The β-blocker propranolol is particularly interesting, as it has been shown not only to upregulate PD-L1 expressed on tumor-associated macrophages (TAM), but also to enhance efficacy of an anti-CTLA4 therapy in soft tissue sarcoma." (PMID 35884428, 2022). "CTLA-4 inhibitors can recognize and eliminate tumor cells by enhancing the activity of antigen-presenting cells and T lymphocytes." (PMID 36246617, 2022). "This involves the use of inhibitory antibodies capable of specifically blocking two receptors that inhibit the anti-tumor immune response of T lymphocytes: PD-1 (Programmed cell death 1) and CTLA-4 (Cytotoxic T-Lymphocyte-Associated protein 4)." (PMID 36286442, 2022).
tumor (continued). "Pharmacological depletion of eosinophils decreased the anti-tumor effect of CTLA-4, thereby promoting tumor growth." (PMID 35186923, 2022). "LAG-3 has been regarded as an indicator of tumor prognosis and become a novel tumor immunotherapy target beyond PD-1/PD-L1 and CTLA-4." (PMID 35958563, 2022). "PD-L1, CTLA-4, tumor microenvironment (TME), and tumor-infiltrating lymphocytes (TILs) status is usually considered biomarkers for immunotherapy." (PMID 35585027, 2022). "Anti-CTLA-4 siRNA-loaded nanoparticles were efficiently internalized by TILs (4–6%) after systemic distribution, resulting in tumor growth reduction and longer survival in B16 F10 melanoma-bearing mice." (PMID 35890239, 2022). "Compared with the control group, the expression of CD4 and CD8 in HCC mice indicated that the local natural immunity of the tumor was activated, whereas the increased PD-1 and CTLA-4 expression indicated the occurrence of immune-suppression." (PMID 35178106, 2022). "Tumor cells can exploit and potentiate the CTLA-4 and PD-1/PD-L1 pathways leading to T cell anergy and T cell apoptosis." (PMID 35043373, 2022). "A high TIDE score indicates a high potential for tumor immune evasion and low likelihood of benefiting from anti-PD-1/CTLA4 therapy." (PMID 36185403, 2022). "Murine CRC models have shown that anti-CTLA4 mAbs induce a potent immune response, rejection of the tumor, and significantly prolonged survival." (PMID 35874729, 2022). "In summary, our work supports blocking of A2AR and TIM3 as an attractive complement to PD-1 and CTLA-4 blockade in anti-tumor immunotherapy." (PMID 35013519, 2022). "In an LS diet cohort, anti-CTLA4 mAb treatment significantly reduced tumor progression (day 35, 339 ± 121 mm3), as compared to isotype mAb (639 ± 163 mm3, p < 0.05)." (PMID 35741331, 2022). "PD1/PD-L1 and CTLA-4 are known to be key immune checkpoints, and they are responsible for tumor immune escape." (PMID 35278064, 2022). "A DNA vaccine coding for gp100 together with IL-12 in combination with CTLA-4/PD-1 blockade treatment significantly inhibited tumor growth in the B16F10-OVA mice model." (PMID 36428682, 2022). "Nevertheless, we observed a decrease in CTLA-4 in tumor samples and CD8 in infiltrating cells of intermediate overweight or obese patients with at least one metastatic lymph node at the diagnosis." (PMID 36358618, 2022). "The deep learning-based framework facilitated automated CTLA-4 quantification in more than 90 different tumor entities via compensating for individual antibody shortcomings." (PMID 35091676, 2022). "Immune checkpoint-related genes, including cytotoxic T-lymphocyte associated protein 4 (CTLA4), programmed cell death-ligand 1 (CD274, PD-L1), and programmed cell death 1 (CD279, PDCD1, PD-1), play vital roles in regulating tumor immune escape." (PMID 36227151, 2022). "Ipilimumab is an anti-CTLA-4 antibody that is approved to treat metastatic melanoma and several other tumor types." (PMID 35979372, 2022). "The successes of immune-checkpoint blockade therapies targeting PD-L1 and CTLA-4 suggest the potential of additional targets to overcome tumor immune suppression." (PMID 36446890, 2022). "The results of monotherapy with anti-CTLA-4, anti-PD-1, and anti-PD-L1 have been modest, and only pembrolizumab in those patients with dMMR has an established clinical use in the context of tumor-agnostic therapy." (PMID 35327339, 2022). "Anti-CTLA-4 mAb can cut off the pathway and enhance the immune responses to tumor cells, such as human IgG1 antibody ipilimumab (Yervoy®)." (PMID 35758066, 2022). "Firstly, we compared the PD-L1 and CTLA4 expression levels between the normal group and the tumor group." (PMID 36419832, 2022). "Previous studies suggested that cancer cells also acquired immune regulatory membrane proteins such as PD-L1, CD4, CD45, CTLA4 and Tim3 expressed in lymphocytes, which in turn contribute to the development of the immunosuppressive tumor microenvironment." (PMID 35794622, 2022).